USP17L22 (ubiquitin specific peptidase 17 like family member 22)
Description:
Deubiquitinating enzyme that removes conjugated ubiquitin from specific proteins to regulate different cellular processes that may include cell proliferation, progression through the cell cycle, apoptosis, cell migration, and the cellular response to viral infection.
Tractability: No criterion of Open Targets' tractability assessment is met for any kind of drug.
Gene: Protein-coding gene on chromosome 4 (9,267,619 to 9,269,211, forward strand). Ensembl gene ENSG00000248933.
Subcellular location: Nucleus; Endoplasmic reticulum
Pathways (Reactome):
Metabolism of proteins: Ub-specific processing proteases
Gene Ontology:
Molecular function: cysteine-type deubiquitinase activity
Biological process: regulation of apoptotic process; protein deubiquitination
Cellular component: endoplasmic reticulum; nucleus
Homologues: Paralogues in human: USP17L11 (99% identical), USP17L19 (99% identical), USP17L20 (99% identical), USP17L17 (99% identical), USP17L18 (99% identical), USP17L24 (99% identical), USP17L25 (99% identical), USP17L26 (99% identical), USP17L27 (99% identical), USP17L28 (99% identical), USP17L29 (99% identical), USP17L30 (99% identical), and 59 more.
Diseases named in the same sentence as USP17L22 in open-access papers:
USP17L22 is named in the same sentence as 4 diseases in open-access papers, as found by Europe PMC text mining. Sharing a sentence is not in itself a finding about the gene and the disease. The quoted sentences say what the papers report.
breast ductal carcinoma (1 paper, 2024). "Entirely new predictions include MAP3K21 (encoding a mixed-lineage kinase) in colorectal cancer, USP17L22 (encoding a deubiquitinating enzyme) in breast ductal carcinoma and TPTE (encoding a tyrosine phosphatase) in lung adenocarcinoma." (PMID 38890488, 2024).
osteosarcoma (1 paper, 2022). A usually aggressive malignant bone-forming mesenchymal neoplasm, predominantly affecting adolescents and young adults. "In order to assess the effect of USP4 and USP17 on PDGFRβ stability, we transiently overexpressed USP4 and USP17L22 in U2OS osteosarcoma cells that naturally express PDGFRβ." (PMID 35064336, 2022).
USP17L22 also shares sentences with these, for which no sentence is quoted: colorectal cancer (1 paper); lung adenocarcinoma (1).